SETDB1 (SET domain bifurcated histone lysine methyltransferase 1)
Diseases named in the same sentence as SETDB1 in open-access papers (continued):
Sharing a sentence is not in itself a finding about the gene and the disease.
breast cancer (continued). "Emerging evidence has revealed the multifunctional role of histone methyltransferase SETDB1 in diseases such as breast cancer and cellular processes." (PMID 35497876, 2022). "Piperlongumine (PL), a natural alkaloid compound, was also reported to be potent in downregulating SETDB1 expression in breast cancer cells." (PMID 36582533, 2022). "Methyltransferase SETDB1 is highly expressed in breast cancer (BC), however, the mechanisms by which SETDB1 promotes BC progression to endocrine therapy resistance remains elusive." (PMID 35395812, 2022). "Knockdown of SETDB1 results in downregulation of breast cancer formation, migration and invasion, and alteration of EMT/MET makers." (PMID 34360879, 2021). "Aberrant expression of SETDB1 has been observed in breast cancer (BC), contributing to tumor progression." (PMID 34440561, 2021). "SET domain bifurcated 1 (SETDB1) is a histone methyltransferase that regulates the expression of Smad7 in breast cancer (BRC) cells." (PMID 34059951, 2021). "For example, miR‐7 inhibits the ability of breast cancer stem‐like cells to spread into the brain through modulating KLF4; miR‐7 directly inhibits SETDB1 and reverses the epithelial–mesenchymal transition of breast cancer stem‐like cells." (PMID 32175684, 2020). "The inhibition of miR-7 by HOTAIR plays a vital role in the suppression of breast cancer stem cell functions by altering the expression of an oncogene, the SETDB1 function." (PMID 32575858, 2020). "Here, we review the biology of SETDB1 and its interacting partners and explain its role in breast cancer metastasis and therapeutic resistance." (PMID 31405032, 2019). "In summary, development of specific SETDB1 inhibitors offers novel therapeutic strategies for metastatic breast cancer, where few options remain to date." (PMID 31405032, 2019). "As well as influencing breast cancer cell migration, invasion, and proliferation, SETDB1 affects stem-cell metabolism/lineage, thus influencing metastatic development." (PMID 31405032, 2019). "In both NMuMG and HMLE breast cancer cell lines, TGF-β stimulation caused a decrease in the levels of SETDB1 as the cells gradually progressed from epithelial to mesenchymal states." (PMID 31137748, 2019). "The overexpression of SETDB1 interacts with these pathways in the breast cancer model and significantly impacts the induction of EMT transcription factors that are associated with metastatic development." (PMID 31405032, 2019). "A deeper understanding of the mechanism via which SETDB1 regulates expression of key genes in breast cancer will help us to develop a more targeted approach to finding an effective and selective inhibitor." (PMID 31405032, 2019). "Here, we discuss the histone methyltransferase SET Domain Bifurcated Histone Lysine Methyltransferase 1 (SETDB1) and its role in breast cancer metastasis." (PMID 31405032, 2019). "This, therefore, signifies the importance for further investigating in histone methyltransferases, such as SETDB1, in breast cancer development." (PMID 31405032, 2019). "SETDB1 is known to contribute to the EMT process in breast cancer by interacting with the SMAD/ transforming growth factor-beta (TGF-B) regulatory pathway that influences EMT-inducing transcription factors such as zinc finger protein SNAI1 (Snail-1)." (PMID 31405032, 2019). "SETDB1 appears to be a central regulator of breast cancer metastasis through the acquisition of stem-cell-like properties, as well as manipulating EMT programs." (PMID 31405032, 2019). "All these findings hinted that the restoration of SETDB1 expression undermined miR-381-3p-mediated retardation on proliferation, cell cycle progression and migration in breast cancer cell lines." (PMID 30309377, 2018).
breast cancer (continued). "In conclusion, our study demonstrated that SETDB1 was upregulated in breast cancer and SETDB1 knockdown suppressed breast cancer progression at least partly by miR-381-3p-related regulation, highlighting SETDB1 as a novel biomarker for breast cancer therapy." (PMID 30309377, 2018). "We found that SETDB1 level was upregulated in breast cancer, and SETDB1 knockdown repressed tumor growth in vitro and in vivo." (PMID 30309377, 2018). "In the present study, SETDB1 was verified to be a functional target of miR-381-3p in breast cancer cells." (PMID 30309377, 2018). "The data also revealed that SETDB1 mRNA level was higher in breast cancer cell lines than that in normal MCF-10A cells." (PMID 30309377, 2018). "The expression level of SETDB1 mRNA in breast cancer tissues and cell lines was firstly assessed by qRT-PCR assay." (PMID 30309377, 2018). "According to the median ratio of SETDB1 mRNA expression, the 45 breast cancer patients were classified into two groups: high SETDB1 mRNA expression group (n = 24) and low SETDB1 mRNA expression group (n = 21)." (PMID 30309377, 2018). "Recently, a research document demonstrated that SETDB1 was regulated by miR-7 played a critical role in the metastasis of breast cancer." (PMID 30309377, 2018). "SET domain bifurcated 1 (SETDB1) has been widely considered as an oncogene playing a critical role in many human cancers, including breast cancer." (PMID 30309377, 2018). "The relative expression of SETDB1 mRNA was significantly elevated in breast cancer tissues compared with normal tissues." (PMID 30309377, 2018). "Subsequently, Kaplan–Meier survival assay and log-rank test using patient post-operative survival were performed to further determine the correlation between the expression level of SETDB1 mRNA and the prognosis of breast cancer patients." (PMID 30309377, 2018). "We verified that SETDB1 mRNA level was upregulated in breast cancer tissues and cell lines, and SETDB1 depletion led to a suppression of cell proliferation, cell cycle progression and migration in vitro, as well as tumor growth in vivo." (PMID 30309377, 2018). "SETDB1 is often amplified in primary breast tumours, and its depletion confers to breast cancer cells growth disadvantage." (PMID 26840455, 2016). "Among the identified Setdb1 genomic targets, Ankrd1 appeared of particular interest due to its involvement in myogenesis and its Wnt/β-Catenin-dependent induction in mammary tumours." (PMID 27790377, 2016). "We identified a list of thirty genes repressed by ΔNp63 in a SETDB1-dependent manner, whose expression is positively correlated to survival of breast cancer patients." (PMID 26840455, 2016). "Here, we found that SETDB1 is overexpressed at protein level in breast cancer cell lines and that its gene is amplified in primary tumours, as also confirmed in a meta-analysis study recently published." (PMID 26840455, 2016). "We showed that SETDB1 is often amplified in primary breast tumours and it is overexpressed at the protein level in breast cancer cell lines." (PMID 26840455, 2016). "We also identified a list of thirty genes repressed by ΔNp63 in a SETDB1-dependent manner, some of them positively correlated to the survival of breast cancer patients." (PMID 26840455, 2016). "We found that mRNA levels of SETDB1 were more than two-fold higher in 14 of 20 breast cancer cell lines." (PMID 25537518, 2015). "Among the five most frequently amplified HMT genes (frequency>10%) in breast cancers, four were localized on the long arm of chromosome 1, with SETDB1 at 1q21.3, ASH1L at 1q22, SMYD2 at 1q32.3, and SMYD3 at 1q44." (PMID 25537518, 2015). "The SETDB1 gene (1q21.3) encodes the H3K9 methyltransferase and showed independent amplification in 23 of 215 primary breast cancers as well as the MCF7 breast cancer cell line." (PMID 25537518, 2015). "It is interesting but elusive whether SETDB1 is important for HIF1α signaling in breast cancer chemotherapy resistance and metastasis." (PMID 38520019, 2024).
breast cancer (continued). "Thus, inhibition of LINC00115 in combination with SETDB1 inhibitors significantly improved the efficiency of paclitaxel chemotherapy in an animal xenograft model of breast cancer metastasis." (PMID 39372872, 2024). "However, METTL13 expression did not significantly differ between HER2-negative and HER2-positive breast cancers, and SETDB1 is a well-known potential modulator of breast cancer metastasis." (PMID 39309445, 2024). "Furthermore, inhibiting LINC00115 in combination with SETDB1 inhibitor markedly improved the efficiency of paclitaxel chemotherapy in an animal xenograft model of breast cancer metastasis." (PMID 38520019, 2024). "C‐MYC could enhance the transcription of SETDB1, making SETDB1 a potential mechanism for driving breast cancer progression." (PMID 37220590, 2023). "Overall, these studies indicate that SETDB1 may act as an oncogenic driver, but is a tumor metastasis suppressor in lung and breast cancers." (PMID 38057834, 2023). "For instance, miR-381 has been reported to repress SETDB1 to inhibit breast cancer proliferation." (PMID 35184652, 2022). "SETDB1 plays an oncogenic role in the progression of many cancers including breast cancer." (PMID 35395812, 2022). "MiR-7 can downregulate SET domain bifurcated 1 (SETDB1), an oncogene that is overexpressed in breast cancer, resulting in the inhibition of tumor progression and metastasis in mice, accompanied by a decrease in the BCSC subset in tumor tissues, as in our previous report." (PMID 32143670, 2020). "In a breast cancer study, the microRNA miR-381-3p successfully downregulated SETDB1 expression, but once SETDB1 expression was restored, SETDB1 overcame miRNA interference, indicating SETDB1 as a potential target for breast cancer therapy." (PMID 31405032, 2019). "An experimental approach to how SETDB1 interacts with EMT-inducing transcription factors in human breast cancers may serve as a valid candidate for further investigation." (PMID 31405032, 2019). "We also outline how targeting SETDB1 may be a valuable therapeutic intervention in breast cancer patients." (PMID 31405032, 2019). "Moreover, knockdown of SETDB1 led to the suppression of breast cancer proliferation and migration in vitro, and also inhibited tumorigenesis in vivo." (PMID 31245293, 2019). "Importantly, a positive correlation between breast cancer patient survival and expression of SETDB1 was noted." (PMID 31137748, 2019). "Moreover, the abnormal expression of SETDB1 protein was found in human breast cancer cell lines by SILAC-based proteomic analysis." (PMID 30309377, 2018). "All these results suggested that SETDB1 knockdown might be sufficient to inhibit cell proliferation, cell cycle progression and migration in breast cancer cell lines in vitro." (PMID 30309377, 2018). "This study revealed that SETDB1 knockdown might suppress breast cancer progression at least partly by miR-381-3p-related regulation, providing a novel prospect in breast cancer therapy." (PMID 30309377, 2018). "Nevertheless, the molecular mechanism by which SETDB1 regulates breast cancer tumorigenesis is still unknown." (PMID 30309377, 2018). "Moreover, miR-381-3p overexpression suppressed cell proliferation, cell cycle progression and migration, whereas SETDB1 abated miR-381-3p-mediated regulatory function on breast cancer cells." (PMID 30309377, 2018). "Furthermore, depletion of SETDB1 results in tumour cell growth disadvantage, indicating that it possibly acts as oncogene also in breast cancer cells in combination with ΔNp63α." (PMID 26840455, 2016). "Functionally, SETDB1 silencing in breast cancer cells results in tumour cell growth disadvantage." (PMID 26840455, 2016). "Our results strongly suggest that in breast cancer, ΔNp63, by physically interacting with SETDB1, could redirect SETDB1 to specific genomic regions and therefore alter H3K9me3 mark responsible for chromatin modification and gene silencing." (PMID 26840455, 2016).
breast cancer (continued). "The authors also identified a list of 30 genes possibly repressed by ΔNp63 in a SETDB1-dependent manner, some of which correlated with the survival of breast cancer patients, suggesting that the ΔNp63α−SETDB1 interaction has a relevant and functional role in breast tumorigenesis." (PMID 27551509, 2016). "Interestingly, SETDB1 protein level is not detected in normal mammary epithelial cells (HMEC), indicating that post-transcriptional mechanisms contribute to SETDB1 accumulation in breast cancer cell lines." (PMID 26840455, 2016). "Having determined that SETDB1 is over-expressed in breast cancer cell lines, we evaluated its functional contribution to the tumor cell growth in vitro by performing a colony forming assay in HCC1954 and MCF-7 breast cancer cells depleted of the expression of SETDB1." (PMID 26840455, 2016). "We found that amplification or overexpression of SETDB1 is more common in basal-like breast cancer." (PMID 25537518, 2015). "Moreover, SETDB1 knockdown may suppress breast cancer progression, at least partly through miR-381-3p-related regulation, as SETDB1 is a verified target of miR-381-3p." (PMID 32391354, 2020). "Therefore, in this review, we illustrate SETDB1 epigenetic activity in breast cancer tissues to potentially influence breast cancer metastasis through the direct and indirect actions on EMT programs via methylation of the histone template, as well as via non-histone substrates." (PMID 31405032, 2019). "Therefore, this study hinted that SETDB1 knockdown might repress breast cancer progression at least partly by miR-381-3p-related regulation, highlighting a novel therapeutic target for breast cancer treatment." (PMID 30309377, 2018). "All these data suggested that SETDB1 knockdown might suppress breast cancer progression." (PMID 30309377, 2018). "Here, we asked whether SETDB1 played a certain role partly by miRNAs regulation in breast cancer." (PMID 30309377, 2018). "Several studies have shown that SETDB1 promotes EMT, tumor progression, and the acquisition of CSC traits in solid cancers, including colorectal and breast cancer." (PMID 41493679, 2026). "These two PROTACs directly penetrate breast cancer cells and effectively recruit the E3 ligase mouse double minute 2 homolog (MDM2) to SETDB1, inducing proteasome-dependent degradation of SETDB1." (PMID 41498743, 2026). "Consistent with these advancements, our analysis reveals SETDB1, NDUFS1, ARMCX5, TRPM4, and SLCO6A1 as significantly altered genes in high-grade breast carcinomas." (PMID 41503337, 2025). "The TCGA-BRCA cohort analysis emphasizes a potential interplay of metabolic genes like NDUFS1, TRPM4, ARMCX5, SLCO6A1, and epigenetic axis genes like SETDB1 and USP37 in the oncogenesis and prognosis of breast carcinomas." (PMID 41503337, 2025). "Piperlongumine, a natural alkaloid compound, has also been found to reduce SETDB1 expression to induce PARP cleavage and FOSB expression in breast cancer cell lines, leading to cell death." (PMID 39583200, 2024). "SETDB1 enhances c-MYC and cyclin D1 expression, and thus provides a growth advantage to breast cancer cells." (PMID 35395812, 2022). "SET domain, bifurcated 1 (SETDB1) restricts HIV-1 replication, while another study showed that miR-381-3p suppresses SETDB1 to inhibit breast cancer progression." (PMID 36685589, 2022). "Reduced SETDB1 induced caspase 9-dependent PARP cleavage and FOSB expression, which mediated the anti-breast cancer effects of PL." (PMID 36582533, 2022). "SETDB1 also enhances the protein expression of c-MYC and CCND1 to promote breast cancer cell cycle progression." (PMID 35372573, 2022). "The regulatory mechanism involves SMAD7, whose expression is regulated by SETDB1, as SETDB1 knockdown upregulated SMAD7 and suppressed metastasis of breast cancer cells." (PMID 34360879, 2021).
breast cancer (continued). "The SETDB1–SMAD-7 interaction was shown to influence cell proliferation, migration, and invasion of breast cancer cells through the activation of EMT programs." (PMID 31405032, 2019). "Furthermore, while we discussed the link of SETDB1 with protein kinases, we cannot exclude the possibility of histone methyltransferase working with phosphatases to regulate gene expression, as nuclear phosphatases were found to be present in breast cancer stem cells and circulating tumor cells." (PMID 31405032, 2019). "Next, we performed quantitative RT-PCR (qRT-PCR) analysis to measure the mRNA expression level of eight HMTs (SETDB1, ASH1L, SMYD2, SMYD3, SETD1A, WHSC1L1, SUV420H1, and SETDB2) in 20 breast cancer cell lines." (PMID 25537518, 2015). "Interestingly, SETDB1 exhibits cell‐type‐specific functions, acting as a suppressor of EMT in lung and breast cancers while facilitating metastasis in hepatocellular and gastric cancers." (PMID 39764697, 2025). "This study also reveals that SETDB1-mediated PLK3 K106/200 methylation not only serves as a key signal driving HIF1α stability and BCSC properties but also acts as a prognostic factor for metastatic breast cancer patients." (PMID 38520019, 2024). "In a study for the treatment of paclitaxel-resistant breast cancer, it was observed that LINC00115 was strongly upregulated in paclitaxel-resistant BCSC, and that LINC00115 acted as an RNA linker recruiting the SETDB1/PLK3 complex to activate the HIF1α signaling pathway." (PMID 39372872, 2024). "At the TP53BP2 gene promoter in HeLa cells and the RASSF1A gene promoter in MDAMB-231 breast cancer cells, SETDB1 interacts with DNMT3A, but not with the maintenance methyltransferase DNMT1." (PMID 38904842, 2024). "Finally, the chromatin modifier SETDB1 was recurrently focally amplified in multiple cancer types, including metastatic NSCLC and primary breast cancer." (PMID 37165135, 2023). "Similarly, during breast cancer, TGF-β activates SMAD3, which recruits SETDB1 to methylate H3K9, while repressing H3K9 acetylation to inhibit the transcription of Snai1 (snail family transcriptional repressor 1) gene." (PMID 38057834, 2023). "However, there are few data illustrating the relationship of SETDB1 to the EMT processes in mouse tumor models and patient tumor tissue samples from metastatic breast cancer patients." (PMID 31405032, 2019). "Notably, we found that eight HMTs exhibited high-level amplification in more than 5% of breast cancers, and five of these eight HMTs (SMYD3, SETDB1, ASH1L, WHSC1L1, and SMYD2) had high-level amplification in more than 10% of samples." (PMID 25537518, 2015). "Considering the critical role of the SETDB1 in contacting and methylating PLK3 and then contributing to drug-resistance and metastasis in LINC00115-driven BCSC, we assessed the effects of TTD-IN treatment combined with LINC00115 antisense oligonucleotides (ASO) on breast cancer metastasis." (PMID 38520019, 2024). "In breast cancer cells, SETDB1 increases the expression of c-MYC to promote cell cycle progression, enhanced growth, and colony formation, and increased c-MYC positive feedback regulates the expression of SETDB1 by directly binding to Setdb1 promoter and enhances its transcription." (PMID 38057834, 2023). "It has been shown that SETDB1 can directly interact with the de novo DNA methyltransferase DNMT3A in order to attach at the promoter region and mediate the transcriptional silencing of well-known tumor suppressor genes RASSF1A (in breast cancer cells) and P53BP2 (in cervical cancer cells)." (PMID 31245293, 2019). "SETDB2’s potentially exclusive function to preserve chromosome fidelity in mitosis may explain the finding that, unlike other methyltransferases including SETDB1, it is frequently downregulated in breast cancer." (PMID 30850015, 2019).
breast cancer (continued). "In contrast, MCF7 showed higher expression of SETDB1, but not ASH1L and SMYD2, which is consistent with amplification of SETDB1, but not ASH1L and SMYD2, in this breast cancer cell line." (PMID 25537518, 2015).